DUSP1 (dual specificity phosphatase 1)
Diseases named in the same sentence as DUSP1 in open-access papers (continued):
Sharing a sentence is not in itself a finding about the gene and the disease.
endometriosis (4 papers, 2020 to 2023). The growth of functional endometrial tissue in anatomic sites outside the uterine body. "MAPK activity could be inhibited in presence of oxidative stress, and DUSP1 overexpression could play a part in this cause-effect phenomenon as described in woman with endometriosis." (PMID 37558907, 2023). "Among the top 20 genes, APOE, DUSP1, MGST1, G0S2, ID4, WEE1, and H2AFZ expression levels were upregulated in the oocytes of patients with endometriosis." (PMID 33467661, 2021).
injury (4 papers, 2021 to 2024). Damage inflicted on the body as the direct or indirect result of an external force, with or without disruption of structural continuity. "DUSP1-mediated dephosphorylation of JNK has been shown to have an antiapoptotic effect in myocardial ischemia-reperfusion (I/R) injury and has been identified as an immune-related diagnostic biomarker for AMI." (PMID 37422588, 2023).
ischemic stroke (4 papers, 2021 to 2025). A stroke disorder caused by obstruction of blood flow to the brain, due to thrombotic (local blood clot formation) or embolic (due to a blood clot or other material traveling from another site) event. "Integrated analyses of ischemic stroke data sets from many previous studies have shown that DUSP1 is overexpressed in both males and females, which suggested that DUSP1 may be a diagnostic biomarker for ischemic stroke." (PMID 35087573, 2021). "Leveraging multiple bioinformatic approaches, we pinpointed a critical gene signature within the ERK pathway—termed GSERK—that prominently included GADD45A, DUSP1, and GADD45B as central modulators implicated in ischemic stroke pathogenesis." (PMID 40636523, 2025). "The ROC curve analysis in the total sample set revealed moderate discriminatory capacity for DUSP1 (AUC = 0.75), GADD45A (AUC = 0.72), and GADD45B (AUC = 0.70), suggesting these genes may serve as potential diagnostic biomarkers for ischemic stroke." (PMID 40636523, 2025). "Our prior work identified DUSP1 as a reliable oxidative stress marker in ischemic stroke." (PMID 40823304, 2025). "Our integration of multiple complementary machine-learning methods, like Boruta, SVM, LASSO, and random forest, provided rigorous confirmation of GADD45A, DUSP1, and GADD45B as robust biomarkers for ischemic stroke, substantially minimizing the risk of false discoveries inherent in genomic analyses." (PMID 40636523, 2025). "Using this approach, we identified a distinct gene signature—termed GSERK—including GADD45A, DUSP1, EREG, IL1B, JUN, and GADD45B as central regulatory nodes within ischemic stroke-related co-expression networks." (PMID 40636523, 2025). "Collectively, these results support the potential of DUSP1, GADD45A, and GADD45B as useful biomarkers for ischemic stroke, warranting further clinical validation." (PMID 40636523, 2025).
metabolic syndrome (4 papers, 2013 to 2023). A cluster of metabolic risk factors for CARDIOVASCULAR DISEASES and TYPE 2 DIABETES MELLITUS. "The DUSP1 gene encodes a member of the dual-specificity phosphatase family previously identified as being differentially expressed in visceral adipose tissue (VAT) of severely obese men with versus without the metabolic syndrome." (PMID 23986905, 2013).
type 2 diabetes (4 papers, 2020 to 2025). "Rosiglitazone induced an increase in both of DUSP1 and DUSP5; while metformin, a first-line treatment for type 2 diabetes, enhanced DUSP5 expression." (PMID 33995033, 2021).
acute lymphoblastic leukemia (3 papers, 2013 to 2023). Leukemia with an acute onset, characterized by the presence of lymphoblasts in the bone marrow and the peripheral blood. "More recently, it has been shown that DUSP1 and Sprouty1/4 are also induced in the lymphoblastic leukemia cell line SUP-B15 after 6 h of DEX treatment, indicating that these negative signaling regulators are part of a transcriptional program triggered by GC in different cellular contexts." (PMID 36818650, 2023). "Similarly, dormant T-cell Acute Lymphoblastic Leukemia (T-ALL) cells showed high levels of phosphorylated ERK1/2 and p38 and low levels of DUSP1." (PMID 33807785, 2021).
Anxiety (3 papers, 2020 to 2024). Intense feelings of nervousness, tension, or panic often arise in response to interpersonal stresses. "Water immersion stress for 24 h induced a state of anxiety and increased serum corticosterone levels and expression of kruppel-like factor-4 in the striatum and dual-specificity phosphatase-1 in the hippocampus." (PMID 33327458, 2020).
E. coli Infection (3 papers, 2011 to 2021). "Interestingly, E. coli infection in DUSP1-deficient mice was reported to result in reduced serum nitrate levels and lower iNOS expression in liver as compared to wild-type mice." (PMID 21547253, 2011).
eczema (3 papers, 2021 to 2025). "Dusp1 partially mediates glucocorticoid effects through its ability to negatively regulate inflammation, is associated with eczema by GWAS89, and has recently been shown to mark an anti-inflammatory set of ILCs69." (PMID 38712036, 2025). "In our meta-GWAS on rare variants in eczema, we uncover disease-associated exonic variants in the genes encoding dual specificity phosphatase 1 (DUSP1), neurogenic locus notch homolog protein 4 (NOTCH4), and solute carrier family 9 member A4 (SLC9A4)." (PMID 34785669, 2021). "The localization of the missense variants and their potential functional impact on the newly-identified eczema-associated genes DUSP1 and NOTCH4 suggest promising targets for future therapies." (PMID 34785669, 2021). "Dusp1 partially mediates glucocorticoid effects through its ability to negatively regulate inflammation, is associated with eczema by GWAS, and has recently been shown to mark an anti-inflammatory set of ILCs." (PMID 40326866, 2025). "As identified in RV set, MAGMA confirmed FLG, DUSP1, and NOTCH4 to be significantly associated with eczema in the complete data set." (PMID 34785669, 2021). "Selecting variants based on the deleteriousness score (CADD) in combination with the variance-component test (SKAT) performed best for the different scenarios and identified FLG, DUSP1, and NOTCH4 to be significantly associated with eczema in RV set." (PMID 34785669, 2021). "We identify rare exonic variants in DUSP1, NOTCH4, and SLC9A4 to be associated with eczema." (PMID 34785669, 2021). "In addition, we found DUSP1 expression to be dysregulated in lesional skin of eczema patients further supporting a role in eczema." (PMID 34785669, 2021). "Interestingly, DUSP1 has been reported to mediate the anti-inflammatory effect of corticosteroids which are a mainstay of eczema therapy." (PMID 34785669, 2021). "Hence, novel therapies directed at modifying DUSP1 function may be beneficial in eczema treatment." (PMID 34785669, 2021).
endometrial cancer (3 papers, 2017 to 2025). Primary or metastatic malignant neoplasm involving the endometrium (mucous membrane that lines the endometrial cavity). "Recently, studies on endometrial cancer have revealed that DUSP1 and AP-1 exhibit a mutual regulatory relationship." (PMID 40535772, 2025). "On the third day, overexpression of DUSP1 indicated a trend toward growth stagnation in the endometrial cancer cells, especially in HEC-1B and HEC-50B." (PMID 37057290, 2023). "Compared with the growth rate of normal endometrial cancer cells as the control, DUSP1 overexpression was found to significantly inhibit the growth of endometrial cancer cells, whereas the knocking down of DUSP1 produced the opposite result." (PMID 37057290, 2023). "Based on our preliminary investigation, DUSP1 was identified as a potential biomarker for endometrial carcinoma prognosis, but its function and mechanism remained unclear." (PMID 37057290, 2023). "Next-generation phosphorylation mass spectrometry was used to explore new downstream target proteins and pathways of DUSP1 in endometrial carcinoma." (PMID 37057290, 2023).
glucocorticoid resistance (3 papers, 2016 to 2019). "In models of glucocorticoid resistance, DUSP1 downregulation can be explained by the deactivation of BDNF signaling, taking into account that DUSP1 is a transcriptional target of BDNF and glucocorticoids." (PMID 31018603, 2019). "Our in vitro and in vivo modeling studies prompted us to assess whether DUSP1 can be considered as a potential therapeutic target for disorders featuring hallmarks of glucocorticoid resistance, one of which is hypercortisolemia." (PMID 27849045, 2016).
hearing loss (3 papers, 2019 to 2021). "Here, we aim to deepen the understanding of the role of DUSP1 in hearing loss, which we began to unveil in our previous paper." (PMID 34572983, 2021). "Overall, our study provides evidence to consider pharmacological modulation of DUSP1 activity as a potential treatment for hearing loss, as an alternative to current SAPK inhibitors." (PMID 34572983, 2021). "We hypothesized that the gene upregulation of the GSH metabolism pathway in Dusp1−/− cochleae might be a consequence of increased ROS production by over-functioning mitochondria that likely drives early and progressive hearing loss in Dusp1−/− mice." (PMID 34572983, 2021). "Thus, the cochlear phenotype of the Dusp1 null mouse reproduces that reported for human ARHL, and shares characteristics with other animal models of progressive hearing loss, including increased apoptotic cell death in the ageing cochlea." (PMID 30938680, 2019). "By contrast, there are no studies exploring the role of DUSP1 in hearing and hearing loss." (PMID 30938680, 2019).
heart failure (3 papers, 2024). Inability of the heart to pump blood at an adequate rate to meet tissue metabolic requirements. "In conclusion, our results demonstrated that CRS-3 induced heart failure by suppressing cardiac DUSP1 expression." (PMID 38322592, 2024). "TMEM87A, PPP2R2A, DUSP1, and miR-92a have great potential as biomarkers for heart failure." (PMID 38886500, 2024). "Ginsenoside Rb1 was shown to regulate the DUSP-1-TMBIM6-VDAC1 axis, inhibiting the release of pro-inflammatory factors and altering the metabolic composition in heart failure mice, protecting the damaged myocardium, consistent with the results of this study." (PMID 39494338, 2024).
mood disorder (3 papers, 2019 to 2022). A cognitive disorder a disturbance in which the person's mood is hypothesized to be the main underlying feature. "Many genes, e.g. FOS, DUSP1 and HNRNPA1, were up-regulated in more than one condition, suggesting potential molecular links between sleep deprivation and mood disorders." (PMID 34691834, 2019).
nonalcoholic fatty liver disease (3 papers, 2016 to 2024). "This technology has been used to silence genes crucial for adipocyte differentiation, such as PPARG and FKBP5, as well as to target three genes (SOCS3, DUSP1, and SIK1) that are upregulated in the adipose tissue of patients with nonalcoholic fatty liver disease (NAFLD)." (PMID 39684387, 2024).
oral squamous cell carcinoma (3 papers, 2017 to 2024). "Further research is needed to confirm the regulatory mechanism between CCR7 and Dusp1 and their impact on the tumor microenvironment of oral squamous cell carcinoma." (PMID 38539232, 2024).
osteoporosis (3 papers, 2021 to 2025). A condition of reduced bone mass, with decreased cortical thickness and a decrease in the number and size of the trabeculae of cancellous bone (but normal chemical composition), resulting in increased fracture incidence. "EVs from M1 macrophages, enriched in miRNA-155, exacerbate bone loss in osteoporosis models by downregulating DUSP1 and activating the JNK signaling pathway." (PMID 40587472, 2025).
preeclampsia (3 papers, 2014 to 2025). Preeclampsia is a hypertensive disorder of pregnancy that is characterized by new-onset hypertension with proteinuria presenting after 20 weeks of gestation, and depending on mild or severe forms may initially present with severe headache, visual disturbances, and hyperreflexia. "Furthermore, we could find only 5 genes (DAPK3, DUSP1, PAPPA2, ITCH, DENND2D) that overlapped with our gender-specific analysis of our data of all early and late combined preeclampsia samples." (PMID 25247495, 2014).
prostate tumor (3 papers, 2021 to 2025). "The results indicated that DUSP1 expression levels were greatly downregulated in primary and metastatic prostate tumors compared to the normal prostate gland." (PMID 38962952, 2024). "In brief, our results demonstrate that DUSP1 decreases Snail expression as well as cell migration and invasion in prostate tumor cells." (PMID 33800291, 2021). "All these data obtained from the experiments carried out with patient samples confirm the results derived from our experimental cell line models and suggest that DUSP1 regulates prostate tumor progression by controlling Snail expression through ERK and JNK inactivation." (PMID 33800291, 2021). "In this analysis of HOX gene expression in prostate tumours and matched benign tissue, we have identified a subset of 14 HOX genes, DFA3_HOX, the expression of which is negatively correlated with ATF3, DUSP1, and Fos." (PMID 40725480, 2025). "Given the potential tumour suppressor roles of DUSP1, FOS, and ATF3, we compared the expression of these genes in prostate tumours and benign prostate tissue." (PMID 40725480, 2025). "In this bioinformatic analysis, we have identified HOX genes that show a negative correlation with Fos, DUSP1, and ATF3 expression in prostate tumours." (PMID 40725480, 2025).
serous ovarian cancer (3 papers, 2021 to 2025). "For example, in high-grade serous ovarian cancer, DUSP1 expression was found to be associated with worse survival in serous ovarian cancer." (PMID 37476896, 2023). "In aggressive serous ovarian cancers, DUSP1 inhibition reduced tumor cell proliferation and limited the tumor progression of patient-derived xenograft models." (PMID 41158869, 2025). "Higher expression of DUSP1 was observed in high-grade serous ovarian cancer (HGSOC), which severely affects progression-free survival (PFS) and overall survival (OS) in patients due to therapy resistance." (PMID 41158869, 2025).
anaphylaxis (2 papers, 2019 to 2023). An acute hypersensitivity reaction that occurs from exposure to an allergen. "Taken together, these results suggested that two hub genes, DUSP1 and CLEC4D, held a promise for the diagnosis of anaphylaxis complicated STEMI as blood diagnostic biomarkers." (PMID 37469874, 2023). "Hub genes identified here (IL1R2, FOS, MMP9, DUSP1, and CLEC4D) represent a whole blood gene signature of anaphylaxis with STEMI predisposition and provide candidate diagnostic and therapeutic targets for follow-up studies." (PMID 37469874, 2023). "IL1R2, FOS, MMP9, DUSP1, and CLEC4D were screened and identified as hub genes shared by anaphylaxis and STEMI." (PMID 37469874, 2023). "Taking the intersection of six algorithms (DMNC, Stress, MCC, Degree, Closeness, Radiality) in cytoHubba, we found 6 hub genes shared by anaphylaxis and STEMI: IL1R2, S100A12, FOS, MMP9, DUSP1, and CLEC4D." (PMID 37469874, 2023). "In this study, we identified four approved drugs that have the potential to be repurposed against hub genes involved in anaphylaxis complicated STEMI, including anakinra, baclofen, andecaliximab, and albuterol targeting IL1R2, FOS, MMP9, and DUSP1, respectively." (PMID 37469874, 2023).
benign prostatic hyperplasia (2 papers, 2021 to 2025). A non-cancerous nodular enlargement of the prostate gland. "Whereas DUSP1 levels are high in benign prostatic hyperplasia (BPH) and hormone-sensitive prostatic adenocarcinoma (HS-PC), the expression of this phosphatase is almost absent in hormone-refractory prostatic adenocarcinoma (HR-PC)." (PMID 33800291, 2021). "A correlation between DUSP1 and the expression of SNAIL, ERK1/2, JNK, and p38 in cell lines (DU145 and PC3) and tissue samples from patients diagnosed with benign prostatic hypertrophy or PC has also been reported." (PMID 40943262, 2025).
cervical cancer (2 papers, 2013 to 2025). A primary or metastatic malignant neoplasm involving the cervix. "Another observation was decreased expression of DUSP1 – a phosphatase gene in cervical cancer samples when compared to normal cervix." (PMID 24403257, 2013). "DUSP1 was downregulated in cervical cancer samples in this study which concurs with published reports." (PMID 24403257, 2013). "From the genes differentially expressed between early and advanced stages of cervical cancer, six genes – three upregulated (BCL3, IGF2, and PIK3R1) and three downregulated (PTPN4, PERP, and DUSP1) were selected for validation by qRT-PCR." (PMID 24403257, 2013).
childhood asthma (2 papers, 2022). "Additionally, upregulation of dual-specificity phosphatase-1 (DUSP1), a negative regulator in the MAPK signaling pathway, to healthy levels and downregulation of inflammatory MAPKs at the gene and protein levels could reduce the prevalence of childhood asthma." (PMID 35586697, 2022).
diabetic cardiomyopathy (2 papers, 2018 to 2019). Diabetic cardiomyopathy is a disorder of the heart muscle in people with diabetes. "In line with this, a decreased expression of DUSP1 in the myocardium of streptozotocin-induced diabetic rats has been reported and suggests a role of DUSP1 and MAPKs in the pathophysiology of diabetic cardiomyopathy." (PMID 30647800, 2018).
eosinophilia (2 papers, 2014 to 2022). "In fact, administration of nematode exosomes to mice suppresses Type 2 innate responses and eosinophilia induced by the allergenic fungus Alternaria, by silencing Il33r and Dusp1." (PMID 35690629, 2022).
esophageal squamous cell carcinoma (2 papers, 2024 to 2025). Esophageal squamous cell carcinoma (ESCC) is a type of esophageal carcinoma (EC) that can affect any part of the esophagus, but is usually located in the upper or middle third. "• DUSP1 silencing reverses the effects of ARNTL in esophageal squamous cell carcinoma." (PMID 39341782, 2024). "Concerning the role of DUSP1 in oesophageal squamous cell carcinoma (ESCC), it was demonstrated that overexpression of the circadian transcription factor ARNTL (also known as BMAL1) upregulates the expression of DUSP1 by inducing its transcription." (PMID 40943262, 2025).
gastric tumor (2 papers, 2020 to 2024). "In conclusion, this study evidenced the upregulation of miR-202-3p in type 1 gNET lesions and suggested it could play critical roles in the pathogenesis of these gastric tumors by repressing translation of DUSP1 mRNA." (PMID 33066578, 2020). "We found that compared with those in normal samples, gastric tumor samples had significantly increased TNF, NOX4, and LONP1 mRNA levels and decreased DUSP1 mRNA levels." (PMID 38758860, 2024).
Hypercholesterolemia (2 papers, 2017 to 2022). An increased concentration of cholesterol in the blood. "A functional impairment in DUSP1 was also found to be associated with a monocyte cellular dysfunction induced by low density lipoprotein in hypercholesterolemia patients." (PMID 36080217, 2022).
hyperlipidemia (2 papers, 2018 to 2024). "LDL reduces the abundance of NK cell protrusions in a Dusp1-dependent manner, which could promote malignancy in individuals W/O and hyperlipidemia." (PMID 39718832, 2024).
invasive carcinoma (2 papers, 2015 to 2024). A carcinoma that is not confined to the epithelium, and has spread to the surrounding stroma. "In addition, we found from Oncomine database that SMEK1 is downregulated whereas JNK signaling target gene DUSP1 is upregulated in human invasive carcinoma." (PMID 26583122, 2015).
kidney clear cell carcinoma (2 papers, 2020 to 2023). "The results of specific staining experiments demonstrated that DUSP1 plays an essential role in the senescence of renal clear cell carcinoma cells by effectively inhibiting the generation of senescent cells." (PMID 37503331, 2023).